SNORA70D (small nucleolar RNA, H/ACA box 70D)
Synonyms: U70D
Gene: Small nucleolar RNA gene on chromosome 16 (71,698,567 to 71,698,701, reverse strand). Ensembl gene ENSG00000263666.
Gene Ontology:
Biological process: RNA processing
Cellular component: nucleolus
Homologues: Orthologues: chimpanzee SNORA70 (96% identical), macaque SNORA70 (90% identical). Paralogues in human: SNORA70I (90% identical), SNORA70 (89% identical), SNORA70G (88% identical), SNORA70H (88% identical), SNORA70J (87% identical), SNORA70 (87% identical), SNORA70C (87% identical), SNORA70B (85% identical), SNORA70 (84% identical), SNORA70E (84% identical), SNORA70 (83% identical), SNORA70F (83% identical), and 16 more.